HMGCS1 (3-hydroxy-3-methylglutaryl-CoA synthase 1)
Diseases named in the same sentence as HMGCS1 in open-access papers (continued):
Sharing a sentence is not in itself a finding about the gene and the disease.
tumor (43 papers, 2015 to 2026). "Correlation analysis of HMGCS1 expression in primary tumors and their pathological features revealed that activation of the mevalonate pathway was associated with tumor size and with the TNM stage." (PMID 36732018, 2023). "In our study, in a cohort of lymph node positive breast cancers, tumour specific HMGCS1 expression was inversely associated with estrogen and progesterone receptors presence, but positively correlated to aggressive disease phenotype." (PMID 32692762, 2020). "Our findings reveal a tumor immune evasion mechanism wherein HMGCS1 drives cholesterol-dependent PM repair by activating the cholesterol synthesis." (PMID 42248910, 2026). "HMGCS1 promotes PM repair by initiating de novo cholesterol synthesis, enhancing tumor cell resistance to lymphocyte-mediated killing and impairing the efficacy of NK, CAR-T, and anti-PD-1-based immunotherapies." (PMID 42248910, 2026). "In contrast, Hmgcs1 and Hmgcr knockdown cells generated tumor masses that were less angiogenic and more prone to basal apoptosis than controls." (PMID 39119789, 2025). "LEC-derived CCL21 induced KAT5-mediated acetylation of HMGCS1 on K273 in GSCs to enhance HMGCS1 protein stability, promoting cholesterol synthesis favorable for tumor growth." (PMID 40277888, 2025). "The same probably applies to Hmgcr knockdown cells, given that these cells can form tumor masses similar to those found in the recipient mice transplanted with the Hmgcs1 knockdown cells." (PMID 39119789, 2025). "In orthotopic liver cancer models, targeting both CSN6 and HMGCS1 effectively suppresses tumor growth under both normal and high-fat diet conditions." (PMID 40521202, 2025). "Further, we collected tumor tissues and found that HMGCS1 overexpression rescued CSN6 KD‐mediated decreased cholesterol and TG levels, and YAP1 target gene expression." (PMID 38308184, 2024). "Further studies of intravenously established mouse models with AML cell lines that over-express HMGCS1 or AML RR primary cells will further illustrate the role of HMGCS1 in tumor growth." (PMID 38994525, 2024). "We confirmed the observed transcriptional upregulation of ITGB4 and the downregulation of ENPP1 and HMGCS1 in BMP4-expressing primary tumours at the protein level." (PMID 39273106, 2024). "To further explore the translational significance of these findings, we established HCC PDX (patient derived xenograft) models from tumor tissues of HCC patients with high CSN6/HMGCS1 expression." (PMID 38308184, 2024). "Overexpression of HMGCS1 can reverse the enhanced lipid metabolism reprogramming and tumor-promoting effects of knockdown of ACSS2." (PMID 38263056, 2024). "The role of ERRα and HMGCS1 in cholesterol metabolism and how this mechanism contributes to invadopodia formation and tumor metastasis require further investigation." (PMID 36835419, 2023). "The expression of ERRα and HMGCS1 in the tumor tissues of the control and XCT790-treatment groups were analyzed by Western blotting and IHC staining." (PMID 36835419, 2023). "This revealed that in both KP and KPL mice, tumour lesions showed upregulation of the Srebp2 target Hmgcs1." (PMID 37202505, 2023). "In conclusion, high expression of HMGCS1 was correlated with poor prognosis in most tumor types, but good prognosis for a small number of tumors." (PMID 34549901, 2022).
tumor (continued). "Reciprocally, the xenografted tumor sizes of NCI-N87 cells infected with lentiviruses expressing the siRNA against HMGCS1 were reduced compared with those of control cells after subcutaneous injection into nude mice (left)." (PMID 32349352, 2020). "In summary, we demonstrated that KLF13 served as a tumor suppressor in CRC through negatively regulating HMGCS1-mediated cholesterol biosynthesis." (PMID 32523679, 2020). "After subcutaneously injecting NCI-N87 cells into nude mice, the xenografted tumor sizes of NCI-N87 cells transfected with the HMGCS1-expressing construct were larger than those of control cells (left)." (PMID 32349352, 2020). "Our study reveals that KLF13 acts as a tumor suppressor in CRC through negatively regulating HMGCS1-mediated cholesterol biosynthesis." (PMID 32523679, 2020). "Accordingly, the xenografted tumor sizes of AGS cells with CRISPR-Cas9-mediated HMGCS1 knockout (upper) were reduced compared with those of control cells after subcutaneous injection into nude mice." (PMID 32349352, 2020). "Consistent with the rate decrease, tumor mRNA and protein expression of HMGCS1, MVK, MVD, and SQLE was also significantly downregulated by XY018 or its combination with statin." (PMID 31604910, 2019). "Importantly, the combination of verteporfin and AAV‐shHMGCS1 treatment was more efficient in hindering tumor growth than verteporfin or AAV‐shHMGCS1 alone in CSN6/HMGCS1 high PDX as demonstrated by reduced tumor volume and reduced tumor weight." (PMID 38308184, 2024). "OE of HMGCS1 could increase tumor growth rates (left, P < .0001) with minimal impact on mouse weight (right)." (PMID 38994525, 2024). "Additionally, a xenograft nude mouse model was established and demonstrated that HMGCS1 overexpression (OE) promotes AML tumor growth." (PMID 38994525, 2024). "Administration of hymeglusin with chemotherapeutic drugs into these mouse models and subsequent analysis of changes in the expression levels of HMGCS1 and tumor burden would provide deeper insight into the efficacy of AML treatment with the combination of hymeglusin and common chemotherapy drugs." (PMID 38994525, 2024). "For AML RR patients, the elevated level of HMGCS1 might also contribute to the growth of AML tumor cells." (PMID 38994525, 2024). "We demonstrated that HMGCS1 promotes tumor growth in a nude mouse model." (PMID 38994525, 2024). "Interestingly, while both tumour subtypes showed increased Hmgcs1 levels compared to normal tissue, Hmgcs1 expression was significantly higher in SCC compared to ADC." (PMID 37202505, 2023). "Furthermore, we used the data of normal tissue from the GTEx dataset as controls to compare the HMGCS1 expression between the tumor and normal tissues." (PMID 34549901, 2022). "Additionally, mitochondrial pyrroline‐5‐carboxylate reductase 2 (PYCR2) and 3‐hydroxy‐3‐methylglutaryl‐CoA synthase 1 (HMGCS1) protein levels were significantly reduced in these tumor lysates." (PMID 35929764, 2022). "Using qPCR, we also found that TGFBR3 and HMGCS1 were downregulated in miR‐223‐OV tumor tissues." (PMID 32491253, 2020). "Restoration of BCL7A expression in cell culture impaired cell proliferation in competition cell growth assay and tumor formation on xenografts in vivo, altering the expression of genes like HMGCS1, H1-0, IRF7, which may help to explain its tumor suppressor role in AML." (PMID 36941700, 2023). "Regarding the mechanisms by which cholesterol induces resistance, it has been reported that CSN6 overexpression in HCC stabilizes HMGCS1, thereby activating YAP1 signaling and promoting tumor progression." (PMID 41232667, 2025). "Conversely, CSN6 antagonizes the ubiquitin ligase activity of SPOP, thereby stabilizing HMGCS1, which in turn activates YAP1 to drive tumor growth." (PMID 40521202, 2025). "Mechanistically, CSN6 antagonizes speckle‐type POZ protein (SPOP) ubiquitin ligase to stabilize HMGCS1, which in turn activates YAP1 to promote tumor growth." (PMID 38308184, 2024).
tumor (continued). "We noted that the transcript levels of HMGCR, HMGCS1 and TM7SF2 were significantly higher in 231-HM cells recovered from primary tumours compared to levels in cultured cells." (PMID 39273106, 2024). "Tumor weight and volume were smaller in the knockdown of ACSS2 group compared to the wild-type group, and further larger in the overexpression of HMGCS1 in ACSS2 knocked down group compared to the knockdown of ACSS2 group." (PMID 38263056, 2024). "Itraconazole induced cell proliferation and apoptosis, and increased HMGCS1 and ACSL4 expression in xenografted tumor A431 cells." (PMID 35242038, 2022). "HMGCS1, GGPS1 and SREBP2 knockdown, in concert with statin-mediated HMGCR inhibition, can robustly enhance tumor cell apoptosis." (PMID 26353928, 2015). "In the case of the depletion of endogenous Hmgcs1, we observed that the lack of metastatic development was likely a mere indirect effect of the reduced tumor masses formed by the knockdown cells in the recipient mice." (PMID 39119789, 2025). "Inhibiting CSN6 or enhancing SPOP activity could promote HMGCS1 degradation, thereby diminishing YAP1 activation and subsequent tumor growth." (PMID 40521202, 2025). "HMGCS1 expression is upregulated in many tumors and can promote tumor progression through both metabolic and non-metabolic pathways." (PMID 38263056, 2024). "The results showed that the high expression levels of ERRα, HMGCS1 and ERRα/HMGCS1 were not different between different tumor stages, histological grades, pathological types, and LNM status (p > 0.05)." (PMID 36835419, 2023). "Restoration of BCL7A hindered cell proliferation in competition cell growth assay and xenograft tumor formation in vivo modulating significantly the expression of genes such as HMGCS1, H1-0, and IRF7, which may help to explain its tumor suppressor role in AML." (PMID 36941700, 2023). "Also, differential expression analysis found that BCL7A restoration altered cell cycle pathways and modified significantly the expression of genes like HMGCS1, H1-0, and IRF7 which can help to explain its tumor suppressor role in AML." (PMID 36941700, 2023). "In hepatocellular carcinoma, abnormal expression levels of cholesterol-metabolism-related genes, such as sterol regulatory element-binding protein 2, HMGCS1, and HMGCR, leads to the lipid reprogramming of tumor cells and promotes the formation of invasive pseudopods." (PMID 36835419, 2023). "Moreover, cholesterol synthesizing enzyme genes HMGCS1 and HMGCR, as well as SREBF2 genes that regulate genes in cholesterol synthesis pathway, all were elevated in tumor and interfacing lymphoid tissues." (PMID 37164975, 2023). "Additionally, 3-hydroxy-3-methylglutaryl-coenzyme A synthase 1 (HMGCS1), as one of cholesterol biosynthesis genes, is impeded in expression level when utilizing the selective PI3Kbeta inhibitor AZD8186 in PTEN-null triple-negative breast cell lines and tumor xenografts." (PMID 35432381, 2022). "This revealed that USP28, SREBP2 and HMGCS1, but not SREBP1, were significantly higher expressed in LSCC tumours (n = 33) compared to LADC tumours (n = 75)." (PMID 37202505, 2023).
infection (11 papers, 2013 to 2025). The state of being infected such as from the introduction of a foreign agent such as serum, vaccine, antigenic substance or organism. "We observed that genes involved in cholesterol uptake (Lrp2) (denoted in grey across the figures) and biosynthesis (Aacs, Hmgcs1, Mvd, Dhcr24) were significantly upregulated during infection; while those implicated in efflux (Abca1, Abcg1) showed a marked downregulation." (PMID 37871034, 2023). "After 48 hours of infection, circHMGCS1 and HMGCS1 expression levels were assessed by qRT-PCR and normalized to GAPDH (n=4)." (PMID 39235443, 2024). "Consistently, the data showed that mRNA levels of Oct4 and SOX-2 in NCI-N87 cells were suppressed after infection with lentiviruses expressing small interfering RNAs (siRNAs) against HMGCS1." (PMID 32349352, 2020). "The decrease in tumorsphere formation in NCI-N87 cells after this combination treatment further deteriorated after infection with lentiviruses expressing siRNAs against HMGCS1 (lower)." (PMID 32349352, 2020). "The repression of HMGCS1 protein after infection was similar to the protein expression changes in the pSILAC data and cells transfected with miR-K11 mimics." (PMID 24039573, 2013). "In contrast, the MTT assay showed that the cell growth reduction caused by combination treatment with lovastatin and dipyridamole was exacerbated by infection with lentiviruses expressing siRNAs against HMGCS1 in NCI-N87 cells (upper) or knockout of HMGCS1 in AGS cells (middle)." (PMID 32349352, 2020). "We found that Mk2206 blocked a robust hypercapnia-induced increase in bronchial epithelial HMGCS1 expression in the absence of infection and prevented increases in expression of SREBP2 and viral NS1 expression in IAV-infected mice breathing elevated CO2." (PMID 40362373, 2025). "Notably, the enzyme HMGCS1, which condenses acetoacetyl-CoA and acetyl-CoA to produce 3-hydroxy-3-methylglutaryl-CoA (HMG-CoA), and the rate-limiting pathway enzyme HMG-CoA reductase (HMGCR) were strongly upregulated even by 2 days post-infection (DPI), prior to the onset of cell proliferation." (PMID 31518366, 2019).
HMGCS1 also shares sentences with these, for which no sentence is quoted: melanoma (5 papers); type 2 diabetes (5); cutaneous squamous cell carcinoma (3); cardiovascular disease (2); colitis (2); endometrial cancer (2); Hypercholesterolemia (2); stomach adenocarcinoma (2); adrenocortical carcinoma (1); atherosclerosis (1); bladder carcinoma (1); bovine tuberculosis (1); cholangiosarcoma (1); depression (1); diffuse large B-cell lymphoma (1); esophageal cancer (1); genetic disorders (1); glioblastoma (1); Huntington disease (1); hypothyroidism (1); lymph node tumor (1); metabolic dysfunction-associated steatotic liver disease (1); neuroblastoma (1); neurodegenerative disease (1); non‐alcoholic steatohepatitis (1); oral squamous cell carcinoma (1); orofacial cleft (1); pancreatic adenocarcinoma (1); pancreatic neuroendocrine neoplasm (1); preeclampsia (1).
A further 7 diseases each share a sentence with HMGCS1 in 1 paper.